CPSF6 (cleavage and polyadenylation specific factor 6)
Diseases named in the same sentence as CPSF6 in open-access papers (continued):
Sharing a sentence is not in itself a finding about the gene and the disease.
infection (continued). "Here, we characterise HIV-1-induced CPSF6 puncta in HeLa cells and primary macrophages and reveal that the puncta form rapidly and continue to be present in cells, associated with CA, for days after reverse transcription and infection occurs." (PMID 38793552, 2024). "To investigate the effects of PF74 in relation to CPSF6-binding of the viral capsid, we performed single-round infections of MDM with wild-type HIV-1 or the CPSF6-recruitment defective A77V variant in the presence or absence of 2.5 μM PF74 and scored infectivity 6d later." (PMID 30672737, 2019). "Importantly, it is not only changes in infection that are associated with an impaired ability of the capsid to engage CPSF6; N74D results in altered integration site targeting in HeLa cells." (PMID 25356722, 2014). "CPSF6 puncta induced by CPSF6 depleted for the MCD upon infection are highly similar to those formed by wild-type CPSF6, suggesting that MCDs do not play a significant role in this process." (PMID 41493399, 2026). "Consistent with previous studies that depleted cellular CPSF6 via RNA interference, CPSF6-KO did not perturb HIV-1 infectivity in HeLa cells, and expression of CPSF6-358 in CPSF6-KO cells potently inhibited infection." (PMID 39823525, 2025). "Our results reveal that infection of CPSF6-NP and MX2 NLS cells resulted in functional nuclear import, as measured by both 2-LTR circles and localization of Gag-Integrase labeled viruses inside the nucleus of these infected cells." (PMID 39823525, 2025). "Subsequently, we assessed infectivity in correlation with the presence of CPSF6 condensates at 120 h post-infection." (PMID 39623137, 2025). "Previously, we showed that capsid binding to cleavage and polyadenylation specificity factor 6 (CPSF6) in the cytoplasm is competitively inhibited by cyclophilin A (CypA) binding and regulates capsid trafficking, nuclear import, and infection." (PMID 40013779, 2025). "We also observed notable strain-specific differences in the phenotype with CXCR4-tropic, CCR5-tropic, and transmitted founder strains having different infection phenotypes in CPSF6 knock-out cells." (PMID 41385587, 2025). "At 5 days post-challenge, in the media only condition, CXCR4 and CYPA knock-out decreased infection while CPSF6 knock-out increased infection as expected." (PMID 41385587, 2025). "For NLSs that conveyed CPSF6 nuclear import, we further showed this defect in infection occurred at the level of viral DNA integration." (PMID 39823525, 2025). "While the magnitude of this effect varies slightly by donor, we observed increased HIV-1 NL4-3 infection upon CPSF6 knock-out in all 41 independent donors used in this study." (PMID 41385587, 2025). "Knock-out of IFNAR1 resulted in a roughly two-fold increase in infection over the NT control compared to the 4- to 5-fold increase observed in the CPSF6 knock-out cells." (PMID 41385587, 2025). "The CPSF6 knock-out infection rate can only increase until it starts to reach the maximum infection rate achievable in the model." (PMID 41385587, 2025). "We achieve nearly complete ablation of CPSF6 protein expression in a majority of our donors by the time spreading infection is initiated, particularly with CPSF6 guide #6." (PMID 41385587, 2025). "Broadly, CPSF6 chimeras that were able to rescue infection by WT HIV-1 were also able to rescue P90A infection to a similar degree, relative to the CPSF6-FL complemented cell line." (PMID 39823525, 2025). "As before, we observed increased infection with our CXCR4-tropic NL4–3 strain at day 5 post-infection in the CPSF6 knock-out cells." (PMID 41385587, 2025). "At day 5 post-challenge, CPSF6 knock-out cells showed a 4- to 6-fold increase in infection relative to the NT controls, indicating that knock-out of CPSF6 enhances infectivity of the N74D capsid mutant." (PMID 41385587, 2025). "Surprisingly, we observed a strong decrease in infection with the CCR5-tropic transmitted founder strain upon CPSF6 knock-out." (PMID 41385587, 2025).
infection (continued). "Immunoblotting of protein lysates harvested from the infected cells demonstrated that CPSF6 protein levels were unchanged between the mock, WT, and N74D infection conditions." (PMID 41385587, 2025). "Next, we correlated the presence of CPSF6 clusters with the efficiency of infection in single cells." (PMID 39623137, 2025). "Given the increase in CXCR4 cell surface expression in the CPSF6 knock-out cells, we next wanted to assess the impact of tropism on the observed infection phenotypes." (PMID 41385587, 2025). "A minimal change in HIV-1 infectivity at 48 hpi was previously reported in CPSF6-depleted Jurkat cells in single-round infection assays." (PMID 40202316, 2025). "Replication-competent HIV-1 NL4-3 showed enhanced infection in CPSF6 knock-out cells compared to the NT control across all tested IFNα doses and the majority of IFNβ doses." (PMID 41385587, 2025). "While the magnitude of this effect varies slightly by donor, we observed increased HIV-1 NL4–3 infection upon CPSF6 knock-out in all 37 independent donors used in this study." (PMID 39678349, 2024). "We also monitored changes in the colocalization of HIV DNA and CPSF6 during infection and entry of cells into quiescence after infection with the pHR′-CD8a-d2EGFP virus." (PMID 38669184, 2024). "Smaller increases in infection upon CPSF6 knock-down have also been observed in other cell types, such as HEK293T and HeLa cells." (PMID 39678349, 2024). "During infection, CA induces the formation of CPSF6 biomolecular condensates, which colocalize with NSs." (PMID 38979149, 2024). "Together, these results reveal the target cell can impact the ability of HIV-1 to utilize chimeric CPSF6-NLS constructs during infection." (PMID 38979149, 2024). "Taken together, our data suggest a model in which CPSF6 recruitment by incoming capsid cores triggers transcriptional reprogramming of infected cells through APA to enhance permissivity to infection." (PMID 39678349, 2024). "We found that the C-MYC and Rac3 NLS not only fully rescued infection, but resulted in a small but significant increase in infectivity compared to the infection observed in CPSF6-KO and CPSF6-FL cells." (PMID 38979149, 2024). "We propose a model wherein CPSF6 perturbation results in broad transcriptional reprogramming and enhanced permissivity to infection, which we demonstrate is mediated in part by enhanced receptor expression and a dampened interferon response." (PMID 39678349, 2024). "The degree of CPSF6 relocalization after infection varies by time and cell type; it remains to be seen to what extent these factors correlate with changes in polyadenylation." (PMID 39678349, 2024). "We, therefore, infected MDMs with different amounts of viral particles and assessed CPSF6 puncta formation by immunofluorescence at different times post-infection." (PMID 38793552, 2024). "In the presence of SQV, CPSF6 knock-out cells maintained a 1.5- to 3-fold increase in infection at both days 2 and 5, suggesting that this increased permissivity is due, at least in part, to changes in the early stage of the lifecycle." (PMID 39678349, 2024). "To understand the impact of these NLSs on infection, we first knocked out endogenous CPSF6 in HeLa cells and generated stable cell lines expressing the indicated CPSF6-NLS chimeras." (PMID 38979149, 2024). "We observed that the addition of NLS sequences that restored the nuclear localization of CPSF6 also promoted the nuclear import of HIV-1 during infection." (PMID 38979149, 2024). "We, therefore, synchronously infected HeLa cells with equal amounts of wild type (WT) and RT-A114V HIV-1-GFP and imaged cells for CA and CPSF6 puncta at different times post-infection." (PMID 38793552, 2024). "To further unveil the function of CPSF6 in virus-triggered innate immune responses, we measured the levels of phosphorylated IRF3 and TBK1 and observed that CPSF6 deficiency markedly facilitated TBK1 and IRF3 phosphorylation after VSV-eGFP infection." (PMID 38416782, 2024).
infection (continued). "Accordingly, ectopic expression of CPSF6 in Cpsf6-/- L929CPSF6 cells inhibited the expression of ISGs upon VSV-eGFP infection and Poly (I:C) or Poly (dA:dT) stimulation." (PMID 38416782, 2024). "Alternatively, disrupting the ability of the capsid to interact with FG-containing cofactors (Sec24C, Nup153, and CPSF6) has also been proposed to inhibit infection." (PMID 38347802, 2024). "CPSF5 showed similar diffuse nuclear staining as CPSF6 in both uninfected HeLa cells and MDMs and relocalised to distinct puncta following infection." (PMID 38793552, 2024). "Our results reveal that infection of CPSF6-NP and MX2 NLS cells resulted in functional nuclear import, as measured by both 2-LTR circles and fluorescently-tagged virus localization." (PMID 38979149, 2024). "We therefore wondered how CPSF6-NLS chimera expression would impact infection with HIV-2 and simian immunodeficiency virus from macaque (SIVmac)." (PMID 38979149, 2024). "At 5 days post-challenge, in the media only condition, CXCR4 and CYPA knock-out decreased infection while CPSF6 increased infection as expected." (PMID 39678349, 2024). "Here, we provide new insights on the properties of CPSF6 protein clusters induced by the infection, and we unravel their unexpected role in HIV-1 pre-integration steps in non-dividing cells, known to be an important cellular reservoir." (PMID 36314049, 2023). "We observed that CPSF6 proteins form condensates that occupy the interchromatin space and host multiple viral components at early time post-infection." (PMID 36314049, 2023). "At 24-, 48-, 72-, and 96-h post-infection, we counted the number of cells containing CPSF6 condensates and normalized the % of cells containing condensates to the total number of cells." (PMID 37414787, 2023). "The percentage of cells containing CPSF6 condensates declined at 48-, 72-, and 96-h post-infection, suggesting that the formation of these structures was transient." (PMID 37414787, 2023). "Relative to WT HIV-1, these viruses are also less sensitive to TNPO3 depletion which enables CPSF6 inhibition of infection." (PMID 37355754, 2023). "Second, we found that CPSF6 clusters increased the volume twice along the time post-infection (72 h p.i. vs. 24 h p.i.)and they were spherical, typical shape of liquid droplets." (PMID 36314049, 2023). "To test the role of capsid-CPSF6 interactions during the infection process, we challenged dog and human cell lines with HIV-1 viruses containing the capsid mutations N74D and A77V (both of which prevent capsid interactions with CPSF6)." (PMID 35215956, 2022). "The CPSF6-358 fragment restricted infection by mixed WT/N74D CA viruses that contained as little as 5% of WT CA present in virus-producing cells." (PMID 35951676, 2022). "To test these possibilities, we allowed CPSF6 to engage with HIV-1 in the nucleus during 8 h of infection, and then added varying concentrations of LEN." (PMID 36202818, 2022). "It is important to emphasize that in our experimental system, CPSF6 KO is performed 15 days after infection with HIV-1, when most of the infectious events have already resulted in integration." (PMID 34154414, 2021). "• Participates in the nuclear import step.• Involved in post-nuclear entry steps.• Favors infection by participating in the nuclear localization of CPSF6." (PMID 33868211, 2021). "Productive infection is further influenced by interactions of CA with host factors, including Cyclophilin A (CypA) and cleavage and polyadenylation specificity factor subunit 6 (CPSF6)." (PMID 34937567, 2021). "Human immunodeficiency virus type 1 (HIV-1) capsid binds host proteins during infection, including cleavage and polyadenylation specificity factor 6 (CPSF6) and cyclophilin A (CypA)." (PMID 33758083, 2021). "CPSF6 is a viral restriction factor that binds to CA lattice in the cell cytoplasm and blocks the infection by enhancing CA stability." (PMID 33573241, 2021).
infection (continued). "CypA prevents capsid from prematurely binding CPSF6 and is consequently vital to the regulation of infection." (PMID 34835048, 2021). "In the early stages of infection, CPSF6–capsid complexes have been observed to traffic on microtubules in the cytoplasm." (PMID 34835048, 2021). "Infection of the WT virus was severely blocked in CPSF6-358-expressing cells, indicating that the WT CA maintained normal levels of CA-CPSF6 interaction." (PMID 31941344, 2020). "As expected, MLV-GFP similarly infected control and CPSF6-358-expressing cells, and CPSF6-358 potently restricted infection by primate lentiviruses." (PMID 32994325, 2020). "Infection of the WT virus was highly restricted in CPSF6-358-expressing cells compared to that in CPSF6-358-FG321/322AA-expressing or SeV− cells." (PMID 31511380, 2019). "To characterize the potential recruitment of CPSF6 to HIV-1 replication complexes at the NPC, we performed two-color STED microscopy of MDM following partial depletion of CPSF6 and infection with wild-type HIV-1 or the A77V variant (carrying IN.eGFP)." (PMID 30672737, 2019). "Conversely, HIV-1N57S infection was inhibited by either TNPO3 or CPSF6 knockdown, only in HOS cells." (PMID 30084827, 2018). "The capsid binding proteins MX2 and, conditionally, CPSF6, both appear to block infection prior to entry in the nucleus." (PMID 26181333, 2015). "Infection of primary monocyte-derived macrophages depleted of CPSF6 reveals HIV-1 to innate immune sensors, leading to induction of an antiviral state and abrogation of HIV-1 replication." (PMID 25356722, 2014). "Our novel findings demonstrate that BI-2, similar to PF74, destabilizes the HIV-1 core during infection and prevents the binding of CPSF6 to the HIV-1 core." (PMID 25496772, 2014). "This work demonstrates that BI-2 destabilizes the HIV-1 core during infection, and prevents the binding of the cellular factor CPSF6 to the HIV-1 core." (PMID 25496772, 2014). "Infection with WT or P90A/A92E CA mutant viruses was inhibited when CPSF6-358 was detected in the cytosol." (PMID 23414560, 2013). "Curiously, although HIV-1 appears to rely upon NUP358, NUP153, TNPO3, and CPSF6 during infection, other lentiviruses only appear to share certain aspects of this mechanism." (PMID 24103892, 2013). "Fate of the capsid assays revealed that cytosolic expression of CPSF6 enhances stability of the HIV-1 core during infection." (PMID 23622145, 2013). "The recovery of efficient infection upon restoration of CPSF6 nuclear transport is consistent with a model in which CPSF6 is a cofactor for HIV-1 nuclear import." (PMID 22956906, 2012). "For instance, M66F reduced the affinity of CA to CPSF6313–327 by 7-fold but only recovered infection in the presence of CPSF6-358 by 3-fold." (PMID 22956906, 2012). "They identified a single point mutation in the viral capsid protein (CA) that allowed efficient infection in the presence of CPSF6-358." (PMID 21994675, 2010). "CPSF6-358 inhibited HIV-1 at an early postentry step in infection, a block that the authors narrowed down to the nuclear import step." (PMID 21994675, 2010). "Moreover, time-course experiments showed that SLFN5 expression increased progressively with infection time, consistent with a temporal window during which capsid–CPSF6 interactions are active in the nucleus." (PMID 41405390, 2026). "However, disruption of CypA binding to the mutant capsid restored nuclear entry, integration, and infection in a CPSF6-dependent manner." (PMID 40013779, 2025). "Furthermore, cells knocked out for CPSF6 exhibit an increase in cGAMP compared to control cells following infection." (PMID 39623137, 2025). "The recent evidence for phase-separated, biomolecular condensates containing CPSF6 and capsid, discussed in Box 1, and their apparent importance in infection is intriguing and suggests HIV as an excellent model to study nuclear phase separation and its biological functions." (PMID 39804283, 2025).
infection (continued). "Understanding CPSF6 puncta formation better will shed light on the role of CPSF6 in infection." (PMID 38793552, 2024). "In addition, dysregulated expression of CPSF6 is also observed in many immune related physiological and pathological conditions, especially in various infections and cancers." (PMID 38416782, 2024). "As CPSF6 puncta are induced by CA in the nucleus independently of reverse transcription, and we previously showed that CA can be detected in nuclear fractions within the first two hours of infection in HeLa cells, we wondered how long it took CPSF6 puncta to form." (PMID 38793552, 2024). "Furthermore, infection of primary CD4 + T cells with wild-type HIV-1 virus recapitulated many of the gene expression changes observed upon CPSF6 knock-out, while infection with an N74D capsid mutant virus recapitulated fewer of these changes." (PMID 39678349, 2024). "Accordingly, mRNA decay assays showed that Cpsf6 mRNAs became more unstable after VSV-eGFP infection or Poly (I:C) stimulation, implicating that the mRNA stability of CPSF6 may be affected by miR-377-3p." (PMID 38416782, 2024). "However, unlike knock-out of the CXCR4 or CYPA dependency factors, which resulted in a consistent drop in infection over a 40-fold range of input virus, the effect of CPSF6 knock-out was dose dependent." (PMID 39678349, 2024). "CPSF6-NLS chimeras show virus-specific influences on infection." (PMID 38979149, 2024). "To test whether CPSF6 condensates were important for infection we utilized hypertonic stress, which prevents formation of CPSF6 condensates, during infection." (PMID 37414787, 2023). "Because hypertonic stress induces the disassembly of HIV-1-induced CPSF6 condensates, we determined whether the formation of condensates is important for infection." (PMID 37414787, 2023). "We also investigated whether the functional partners of CPSF6 are recruited to the condensates upon infection." (PMID 37414787, 2023). "To determine whether CPSF6 condensates play a role in infection, we challenged human cells with HIV-1 in a hypertonic medium that prevents the assembly of CPSF6 condensates during infection." (PMID 37414787, 2023). "These experiments suggested that the CPSF6 condensates formed upon infection that serve an unknown function are subsequently disassembled." (PMID 37414787, 2023). "Infection with shCPSF6 efficiently knocked down CPSF6 expression at both mRNA and protein levels." (PMID 36446361, 2022). "The competitive interactions of CypA and CPSF6 were quantified by using live cell microscopy, by which fluorescently labelled CPSF6 colocalized with trafficking PICs, presumably through binding to the capsid, in the cell cytoplasm after infection." (PMID 34835043, 2021). "In conclusion, we hypothesise that during a productive infection, a capsid remodelling step takes place at the nuclear pore that releases the core complex from Nup153, and relays it to CPSF6, which then localises it to chromatin ready for integration." (PMID 34543344, 2021). "For example, infection by viruses with mutated CA that no longer interact with several of these factors (CPSF6, CypA, and Nup358), triggers an interferon-mediated antiviral response in human monocyte-derived macrophages." (PMID 33868211, 2021). "Therefore, to investigate the interaction between our hyper-stable mutants and CPSF6, we monitored the reorganisation and redistribution of CPSF6 to nuclear speckles during infection." (PMID 34543344, 2021). "In the context of the lower infectivity of the Q4R viruses, there may be concerns about the results of our infection assay in CPSF6-358-expressing cells." (PMID 31941344, 2020). "However, similar to previous experiments, removing CPSF6 only modestly reduced the infection levels in macrophages because the capsids used the remaining low CPSF6 levels." (PMID 30834893, 2019).